HGF (hepatocyte growth factor)
Diseases named in the same sentence as HGF in open-access papers (continued):
Sharing a sentence is not in itself a finding about the gene and the disease.
tumor (continued). "Nakagawa and colleaguesobserved that tumor-secreted (not stromal secreted) HGF could induce resistance to theVEGFR inhibitor lenvatinib, and that this resistance could be overcome by co-treatmentwith golvatinib, a MET inhibitor." (PMID 25490933, 2014). "However, no HFD-induced increase in mammary gland or tumor expression of HGF was observed in the present study." (PMID 24156623, 2013). "Although it is still unclear whether NK4-like fragment is generated via an enzymatic cleavage or variant transcription, NK4-like fragment(s) could act as a natural HGF-antagonist to minimize tumor metastasis (as a negative feedback)." (PMID 23296269, 2013). "When rat HGF cDNA was introduced into immortalized mouse liver epithelial cells (MLE10), all MLE10-HGF cell lines grew much faster than the original MLE10 cells in culture and produced in large colonies in soft agar, suggesting the involvement of aberrant MET signals in tumor onsets." (PMID 23296269, 2013). "Similarly, ErbB2-driven tumor cells are EGFR-dependent and also display HGF-mediated rescue." (PMID 23028720, 2012). "Really, our data, showing an increase in fibroblast secreted VEGF-A, HGF, and SDF1, are in keeping with others emphasizing that tumour dissemination could be facilitated by the myofibroblastic component of the stroma through the secretion of invasion associated-secreted factors." (PMID 22272371, 2012). "The HGF/c-MET pathway might play a key role in prostate carcinogenesis and tumour progression." (PMID 22110593, 2011). "PCBP1 could inhibit the v6 expression induced by Ras activation and HGF and then break the positive feedback loop, suggesting that PCBP1 might function as a candidate tumor suppressor and play a potential role in the gene therapy of malignant tumors with v6 overexpression." (PMID 20361869, 2010). "For example, stromal fibroblasts or tumor associated fibroblasts (TAFs) modulate the environment by secreting growth factors (such as HGF and PDGF), and therefore the tumor microenvironment may drive tumor growth and even selectively support a subset of tumor cells, such as CSCs." (PMID 24281215, 2010). "PDGFRA may regulate tumor angiogenesis by PDGFRA-p70S6K pathway which is related to the function of fibroblast growth factor (FGF) and expression of VEGF and hepatocytes growth factor (HGF)." (PMID 19948069, 2009). "However, the contribution of HGF to tumorigenesis was not elucidated in this experiment, as mouse HGF could also contribute to tumor growth." (PMID 41184222, 2025). "For instance, tumor-related fibrous cells may release HGF, a tumor mortality factor, to encourage the growth of the tumor microenvironment, while CD8+ T lymphocytes may secrete cell factors to regulate tumor progression, create blood vessels, and build the tumor microenvironment." (PMID 38980253, 2024). "Regardless of the mechanism involved, the presence of HGF in NSCLC tumours harbouring MET exon 14 skipping strongly indicates the presence of an HGF‐METex14 signalling axis in these patients, which may have a deep impact on a ligand‐dependent oncogene addiction." (PMID 36799689, 2023). "Moreover, DK1 also enhanced the expression of several other tumor suppressor genes that are related to this pathway such as FOXO, TP73, CDKN1A, Caspase, CYCS, and GADD45A while impeded the expression of other proto-oncogenes namely PIK3R3, BCL-2, IGFBP2, HGF, and FGF." (PMID 34204873, 2021). "The results showed that hGF and PTX3 expression was downregulated and S100P expression was upregulated in LUAD, and that the expression of all the three was correlated with immune cell infiltration, suggesting that all the three gene could promote tumor progression." (PMID 34745947, 2021). "The derived cells expressed MSC-related marker, secreted angiogenic and immune regulatory factors in levels comparable to that of UC-MSCs, except for HGF, and could be induced to experience chondrogenic and adipogenic differentiation, and more importantly did not form a tumor in vivo." (PMID 33381545, 2020).
tumor (continued). "The MET kinase inhibitor SU11274 has been studied in non-small cell lung cancer xenografts resulting in inhibition of tumor growth, but whether pharmacological administration of HGF can lead to cancer development in the absence of oncogene or tumor suppressor alterations is unclear." (PMID 32372975, 2020). "On the other hand, AMPK could attenuate angiogenesis induced by tumor-promoting and pro-metastatic factors, such as the phosphoinositide 3-kinase /protein kinase B (Akt)/mammalian target of rapamycin (PI3K/Akt/mTOR), hepatic growth factor (HGF), and TGF-β/BMP signaling pathways." (PMID 31331111, 2019). "Lipopolysaccharide-stimulated MAPK and Hepatocyte growth factor (HGF) signaling were activated in the newly differentiated hepatocytes (GFP+R) but not in the tumor-reverted hepatocytes (RFP+R), indicating that these activities may be required in nascent hepatocytes." (PMID 31515263, 2019). "Our findings may thus indicate that targeting of HGF, a novel microenvironmental factor involved in CLL pathogenesis, could improve conventional therapies to cure this disease by inhibiting leukemic cell growth and by restoring specific immune responses against the tumor." (PMID 30642077, 2019). "However, gemcitabine and HGF inhibition alone or in dual combination did not influence cancer cell apoptosis; hence the reduced tumor volumes in these mice could be due to reduced proliferation rather than increased apoptosis of cancer cells." (PMID 29100344, 2017). "Interestingly, FLOT1 has been reported to be crucial for coordinated assembly of signaling complexes and signal transduction induced by TNF-α, EGF, HGF and IGF-l, suggesting that FLOT1 might play an important role in mediating the heterotypic signals originate in the tumor microenvironment." (PMID 26646322, 2016). "Similarly, in cohort 2, tumours with increased HGF copy number tended to be ER negative." (PMID 27175600, 2016). "Importantly, HGF antagonism translated into the emergence of antigen-specific CTL, as shown by the strong cytotoxic responses against parental B16-F10 melanoma cells and E.G7-OVA lymphoma cells achieved using splenocytes from tumor-bearing mice treated with NK4 and DC." (PMID 22567028, 2012). "Recent data have indicated that matriptase may have a role in the activation of hepatocyte growth factor and it will be of interest to determine whether this is integral to its action in the prostate, where there is evidence for participation of increased HGF-Met signalling in tumour progression." (PMID 15928670, 2005). "Furthermore, the survival rate of patients with both intratumoral c-Met-positive and stromal HGF-positive tumours was significantly lower than for patients with either positive tumours, and that of patients with both negative tumours (P=0.0183 and P=0.0011, respectively)." (PMID 15083185, 2004). "It is suggested that hepatocyte growth factor (HGF), which is secreted by fibroblasts located in specific tumor microenvironments, increases WNT signaling and endows non-CSCs with self-renewal and tumorigenic capabilities." (PMID 39695175, 2024). "We treated ER+ tumor cells (MCF7) with fulvestrant in the presence or absence of the top five secreted cytokines (GROα/CXCL1, IL-8, CXCL5, hepatocyte growth factor (HGF) and CCL19)." (PMID 37423299, 2023). "While many clinical trials targeting HGF/C-MET axis are ongoing or have been completed, most results have not demonstrated complete tumor regression and definitive evidence of target engagement." (PMID 37919751, 2023). "Therefore, tumor HGF may not be a feasible biomarker for SCLC." (PMID 37828456, 2023). "It has been shown that the Hepatocyte growth factor (HGF) is over-expressed in HCC compared to the normal and cirrhotic liver without signs of neoplasia." (PMID 36675666, 2022).
tumor (continued). "No significant alterations were observed for HGF in GSE20347 dataset, while GSE45670 showed HGF downregulation in tumors relative to non-tumor surrounding tissue (fold-change=-3.72), and GSE75241 presented HGF overexpressed in ESCC patients (fold-change=2.11)." (PMID 34037097, 2021). "Teliso‐v targets c‐Met–overexpressing tumor cells, irrespective of MET gene amplification status, resulting in blockade of both HGF‐dependent and HGF‐independent c‐Met signaling." (PMID 33675179, 2021). "In the study of EMD 1214063 and EMD 1204831, both candidates triggered tumor regression in a dose-related fashion by inhibiting c-MET phosphorylation, regardless of HGF-dependent or HGF-independent activation." (PMID 35087755, 2021). "Immunohistochemistry for HGF and the c-MET receptor has been investigated in eight patient bronchioaveolar lavage (BAL) samples and five paired tumor and adjacent non-tumor tissue samples from patients with bronchioaveloar carcinoma (BAC)." (PMID 32117721, 2020). "Neither secretion of adipocyte specific cytokines (leptin and adiponectin) nor angiogenesis factors (VEGF, HGF) or MCP1 and IL6 discriminate fat tissues from tumor-bearing (AdipTa or AdipTd) and tumor-free breasts (AdipN)." (PMID 32974182, 2020). "Hepatocyte growth factor (HGF) rather than other growth factors, like epidermal growth factor (EGF), was observed an immediate outburst in the sera of forty HCC patients after tumor resection." (PMID 32206115, 2020). "In pancreatic cancer, HSPG-mediated activation of HGF/c-MET signaling induces proliferation and migration of tumor cells through the activation of ERK1/2 but not the AKT pathway." (PMID 32916872, 2020). "Although MetMab failed to inhibit METamp cell proliferation and tumor growth, both INC280 and MetMab reduced HGF-autocrine tumor growth." (PMID 30208970, 2018). "Median levels of proinflammatory cytokines (IL-6 and IL-8), HGF, and OPN tended to be lower at the end of the study in individuals exhibiting tumor response in comparison with subjects with no response." (PMID 30651923, 2018). "This uptake was enhanced by HGF or EGF (not shown), suggesting GF induction of endocytic activity in the tumor cells." (PMID 29796184, 2018). "Neither of the recombinant proteins for HGF or VEGF promoted tumor cell proliferation, nor did their neutralizing antibodies suppress Ad-CM-promoted tumor cell proliferation." (PMID 28989976, 2017). "Taken together, we confirmed HGF as a tentative predictive biomarker, which in our cohort was predictive for the efficacy of EGFRI therapy irrespective of the tumor site." (PMID 28456787, 2017). "Concomitant targeting of GLUT1 and HGF potently suppressed growth and dissemination of AI-resistant human tumors in human HGF knock-in SCID mice without exacerbating tumor hypoxia." (PMID 28445144, 2017). "For in vitro receptor activation, the medium was supplemented with a mixture of the growth factors EGF, HRG, HGF and IGF to compensate for the absence of tumor–stroma interactions." (PMID 27578890, 2016). "The mutual interaction between OBs and tumor cells within the bone milieu has been extensively studied; however, whether a specific subset of osteolineage cells contribute to the pathogenesis of skeletal metastases, via the HGF/MET pathway in particular, has not yet been elucidated." (PMID 26934743, 2016). "In contrast, SRI 31215 prevented fibroblast-induced MET activation and signaling in tumor cells, but did not prevent MET activation induced by active HGF." (PMID 27121052, 2016). "Furthermore decrease of apoptotic cells after HGF addition to canertinib 2 uM in Res-259 cells and after EGF addition to sorafenib 1 uM in Res-196 cells, could also be exceeded by crizotinib or canertinib respectively (61,5% and 36.9% more apoptotic tumor cells)." (PMID 25799134, 2015).
tumor (continued). "The existence of a cooperative mechanism between adhesion molecules and Met protein is also suggested by the observation that adhesion of tumor cells to ECM components, by itself, induces Met protein activation, even in the absence of HGF." (PMID 28548071, 2014). "Collectively, these results demonstrate that under hypoxic conditions, HIF-1β expression regulates the expression of various tumor growth-related factors, namely EGF, HGF, and VEGF, but not FGF2." (PMID 25068796, 2014). "Collectively, these data suggest that under hypoxic conditions, HIF-1β expression regulates the expression of tumor growth-related factors, namely EGF and HGF, but not FGF2." (PMID 25068796, 2014). "Overexpression of MACC1 induces down-stream activation of HGF/c-Met and promotes metastasis of colon cancer, while silencing of MACC1 leads to reduced tumor proliferation, decreased cell migration, and a lack of new metastasis." (PMID 23414367, 2013). "Binding of the LMH 87 and LMH 88 antibodies to an epitope in the α-chain portion of the c-MET β-propeller promoted receptor degradation independent of HGF/SF, leading to reduced levels of surface c-MET in tumor cells." (PMID 22511956, 2012). "In contrast, although the HGF antibody rilotumumab (AMG102) has shown some anti-tumor effects in preclinical trials, its combination with bevacizumab did not significantly inhibit tumor growth and resulted in high toxicity." (PMID 41141394, 2026). "The bias in tumor cell proliferation toward peristromal niches under ALKi therapy was not limited to alectinib treatment, as lorlatinib induced a similar effect in H3122 tumors grafted in regular NSG mice that lacked the functional HGF-cMET axis." (PMID 40313737, 2025). "While we did not directly assess tumor repolarization, it is reasonable to propose that inhibition of the c-MET/HGF axis may indirectly promote a shift in the TME." (PMID 41289612, 2025). "In order to evaluate whether these compounds demonstrated greater toxicity to neoplasms than non-malignant cells, 1a–n were evaluated against HSC-2, HSC-3, HSC-4 and HL60 neoplasms as well as non-malignant HGF, HPC and HPLF cells." (PMID 39584969, 2024). "These lines of experimental evidence demonstrate the critical role of HGF/MET and Wnt/β-catenin signaling co-activation in promoting tumor progression and inducing AR and SYN double-negative tumor cells, which is similar to what we have observed in PCa patient samples treated with current ADT." (PMID 38336745, 2024). "Interestingly, all the tumours displaying HGF expression had high METex14 expression (IHC2+ and IHC3+) but without MET or HGF gene amplification as determined by fluorescence in situ hybridisation of MET (FISH) and comparative genomic hybridisation (CGH)." (PMID 36799689, 2023). "As PSCs do not express the MET receptor, inhibition of the HGF/MET axis by the Combo treatment cannot directly influence the PSC status, but must be the consequence of a cross-talk between the tumor and the stroma compartment, which probably occurs through TNC." (PMID 34298732, 2021). "Because HGF, but not EGF, significantly alleviated the suppressive effect of Cfd-KO mADSCs on tumorsphere formation in vitro, we evaluated the effect of HGF to alleviate the suppressive effect of Cfd-KO mADSCs on tumor formation in vivo." (PMID 34439392, 2021). "Moreover, in tumor cells, Met is able to bind EGFR and to be phosphorylated without an upstream HGF activation." (PMID 28446239, 2017). "Interpretation of the relative roles of HGF and VEGF in xenografts is complicated by the fact that mouse stromal cell derived HGF does not efficiently activate human cMET and therefore makes no contribution to tumor growth." (PMID 29228696, 2017).
tumor (continued). "However, dual combinations i.e HGF inhibition + c-MET blockade, HGF inhibition + gemcitabine and c-MET blockade + gemcitabine did not exhibit any additive effect in terms of tumor reduction." (PMID 29100344, 2017). "Furthermore, only one hHGF negative mouse of 5 injected with MET-T1010I expressing tumor cells developed a tumor and none of the MET-WT or MET-Y1253D cohorts developed tumors indicating that human HGF is required for optimal tumor development in SCID mice." (PMID 25605252, 2015). "The efficacy of V-4084 in inhibiting tumor growth was tested against orthotopic tumors, in which a firefly luciferase reporter gene was transferred into GBM cells with (U87M2) and without (DBM2) endogenous HGF expression." (PMID 26381735, 2015). "In addition, DIDS and H2DIDS reduced hepatocyte growth factor (HGF)-induced, but not epidermal growth factor (EGF)-induced, cell scattering, wound healing, and 3-dimensional (3D) proliferation of tumor cell spheroids." (PMID 26543230, 2015). "This does not however rule out any functional differences that may contribute to tumor development such as the storage and release of pro-angiogenic mediators including VEGF and HGF, which warrants further investigation." (PMID 25978773, 2015). "HGF mRNA is not found in normal hepatocytes, but expressed in a high percentage of HCC, and in fact, in vivo data support a role for the autocrine HGF/Met axis in tumor promotion." (PMID 23936038, 2013). "This is consistent with the analysis of MET expression by conventional RT–PCR, which shows expression of MET mRNA in all 19 tumours with no known translocation: quiescent satellite cells normally express MET, the receptor for hepatocyte growth factor, prior to entering S-phase." (PMID 12865925, 2003). "However, the detection of HGF overexpression and MET activation without MET gene alterations is challenging because of the heterogeneity of HGF‐producing fibroblasts and instability of MET phosphorylation in tumor specimens." (PMID 36416133, 2023). "Here we show, by genome editing of the nontransformed lung epithelial cells 16HBE, that HGF‐activated METex14 when expressed at the endogenous level, in the absence of MET amplification or other genetic alterations, transforms these cells in vitro and, importantly, induces tumour formation." (PMID 36799689, 2023). "Expression of HGF and its receptor supports the existence of both autocrine and paracrine mechanisms of HGF action in HCC if compared to the unique paracrine mechanism found in normal liver tissue (in the absence of cancer), suggesting that it also plays a role in tumor development and progression." (PMID 36675666, 2022). "Finally, we demonstrate that local/tumor HGF expression may be required to convey resistance to BRAF inhibition in vivo, observing rescue when HGF is expressed in the tumor microenvironment but not when expressed systemically." (PMID 28147313, 2017). "The onset of αSMA stress fibres in stromal cells is not therefore directly coupled to their tumour-modulating function; and a better surrogate indicator of stromal functionality may be the secretion of certain factors including SDF-1, VEGF and HGF." (PMID 25596732, 2015). "In addition, STMN1, MET, and HGF were expressed at similar levels in primary PCa tissues and mCRPC lesions in bone, adrenal gland, lung, lymph node, peritoneum, and bladder, inferring that the levels of STMN1, MET, and HGF expression were independent of any observed tumor heterogeneity between men." (PMID 40723207, 2025). "Moreover, our results also indicate a significantly positive correlation among leptin, IL-6, TNF-α and HGF and TNM stage, and a significantly negative correlation between adiponectin and TNM stage; suggesting that it should be considered as an important factor in tumor growth." (PMID 29088874, 2017).